PRR23B (proline rich 23B)
Synonyms: FLJ46116
Tractability: No criterion of Open Targets' tractability assessment is met for any kind of drug.
Gene: Protein-coding gene on chromosome 3 (139,019,031 to 139,020,926, reverse strand). Ensembl gene ENSG00000184814.
Subcellular location (Human Protein Atlas): Microtubules; Nucleoplasm; Cytokinetic bridge; Cytosol; Mitotic spindle; Nuclear bodies
Gene Ontology:
Molecular function: protein binding
Genetic constraint (gnomAD): Loss-of-function variants: 0 observed, 0.7 expected, observed/expected ratio (o/e) 0, 90% interval 0 to 1.8. That is too few expected variants to judge how well the gene tolerates losing a copy. Missense variants: 375 observed, 355.27 expected, observed/expected ratio (o/e) 1.06, 90% interval 0.97 to 1.15. Synonymous variants: 157 observed, 160 expected, observed/expected ratio (o/e) 0.98, 90% interval 0.86 to 1.12.
Homologues: Orthologues: chimpanzee PRR23B (99% identical), rat Prr23a1 (45% identical), rat Prr23a2 (45% identical), mouse Prr23a1 (44% identical), rat Prr23a3 (44% identical), mouse Prr23a3 (43% identical), mouse Prr23a2 (43% identical), rat Prr23d1 (37% identical), mouse Prr23a4 (23% identical). Paralogues in human: PRR23A (90% identical), PRR23C (85% identical), PRR23D1 (26% identical), PRR23D2 (26% identical), PRR23E (19% identical).